PLAC1 (placenta associated 1)
Diseases named in the same sentence as PLAC1 in open-access papers (continued):
Sharing a sentence is not in itself a finding about the gene and the disease.
diabetes (2 papers, 2008 to 2013). "Placental specific protein 1(Plac1), was designated as candidate gene because Plac1was regarded as a marker for placental development, which was widely associated with prenatal growth and adult endocrine related disorders such as pubertal timing, obesity and diabetes." (PMID 18725948, 2008). "Preliminary examination of placentae obtained at various gestational ages revealed no discernable effect of diabetes or preeclampsia on PLAC1 expression." (PMID 23840959, 2013). "Although there was no apparent difference in PLAC1 gene expression among human pregnancies complicated by diabetes or preeclampsia, an unexpected effect of labor was noted at term." (PMID 23840959, 2013).
endometrial serous adenocarcinoma (2 papers, 2013 to 2014). A high grade, aggressive adenocarcinoma arising from the endometrium. "Further, we find that PLAC1 expression is significantly higher in the more advanced, more aggressive endometrial serous adenocarcinomas and carcinosarcomas relative to endometrioid adenocarcinomas by more than 6-fold and 16-fold, respectively." (PMID 23935632, 2013). "Moreover, we show that PLAC1 expression is significantly greater in the higher stage, more aggressive uterine serous adenocarcinomas and carcinosarcomas." (PMID 23935632, 2013).
endometrioid tumor (2 papers, 2013 to 2014). A benign, borderline, or malignant epithelial tumor of the female reproductive system characterized by the presence of glands and/or cysts lined by neoplastic cells that resemble endometrial cells. "However, the higher stage, more aggressive serous adenocarcinomas and carcinosarcomas did display significantly higher PLAC1 expression than the lower stage, less aggressive endometrioid tumors." (PMID 23935632, 2013).
Intrauterine Growth Restriction (2 papers, 2014). "The importance of PLAC1 to the establishment and maintenance of normal gestation has been amply demonstrated through the generation of a Plac1 knockout mouse model in which placentae exhibit placentomegaly and pups show numerous phenotypes consistent with intrauterine growth restriction (IUGR)." (PMID 24757447, 2014).
melanoma (2 papers, 2016 to 2024). A malignant, usually aggressive tumor composed of atypical, neoplastic melanocytes. "The underlying idea of using placental antigens as effective cancer vaccines led to our recent observation that immunization with placenta-specific 1 (PLAC1), a membrane-associated protein, delays tumor onset and increases survival in a mouse model of melanoma." (PMID 38707901, 2024).
nasopharyngeal carcinoma (2 papers, 2024 to 2025). A carcinoma arising from the nasopharyngeal epithelium. "PLAC1 is classified as a cancer/testis antigen (CTA), with elevated expression reported in several tumor types, including stomach, colon, liver, pancreas, prostate, ovary, uterus, cervix, breast, lung, HNSC and nasopharynx carcinoma." (PMID 40607388, 2025).
non-small cell lung carcinoma (2 papers, 2014 to 2021). A group of at least three distinct histological types of lung cancer, including non-small cell squamous cell carcinoma, adenocarcinoma, and large cell carcinoma. "PLAC-1 is found in colorectal cancers and non-small cell lung cancer (NSCLC)." (PMID 33916290, 2021).
preeclampsia (2 papers, 2013 to 2023). Preeclampsia is a hypertensive disorder of pregnancy that is characterized by new-onset hypertension with proteinuria presenting after 20 weeks of gestation, and depending on mild or severe forms may initially present with severe headache, visual disturbances, and hyperreflexia. "We examined PLAC1 gene expression in the human placenta during normal pregnancy and pregnancies associated with maternal diabetes and preeclampsia using quantitative, real time PCR (q-RT-PCR)." (PMID 23840959, 2013). "We have examined the expression of PLAC1 gene expression during normal human pregnancies and pregnancies associated with maternal diabetes and preeclampsia." (PMID 23840959, 2013). "Moreover, increased plasma levels of PLAC1 mRNA were observed in the preeclamptic patients and were explained by the damage to placental villi and the apoptosis of trophoblast cells due to the oxidative stress associated with preeclampsia." (PMID 36835024, 2023). "Subsequently, elevated levels of circulating PLAC1 mRNA were observed in pregnancies complicated by preeclampsia and were directly related to disease severity." (PMID 23840959, 2013). "Although its role has not been defined, increased circulating levels of human PLAC1 mRNA in maternal blood are associated with preeclampsia." (PMID 23840959, 2013). "This significantly higher concentration of PLAC1 protein could derive from an abnormal shedding of PLAC1 antigen, probably related to an aberrant function of proteolytic enzymes, MMP-2 and/or MMP-9, associated with preeclampsia as previously reported in literature." (PMID 36835024, 2023). "We suggest that the aberrant functioning of MMPs could cause an abnormal PLAC1 antigen shedding, which could in turn be responsible for the enhanced trophoblast proliferation and the excessive collagen deposition previously found to be associated with MMP defects and preeclampsia." (PMID 36835024, 2023). "A decrease in pregnancy-associated plasma protein A (PAPPA), a syncytiotrophoblast-derived metalloproteinase, and, in accordance with our results, an increase in PLAC1 expression was demonstrated in pregnancy complicated by preeclampsia as compared with non-PE controls." (PMID 36835024, 2023).
prostate adenocarcinoma (2 papers, 2016 to 2022). "On the other hand, placenta-specific protein 1 (PLAC1) is expressed in prostate adenocarcinoma." (PMID 35012580, 2022). "Thus, MAGEA3 and PLAC1 may have some prognostic value, as observed in nonsmall lung cancer, renal carcinoma, or prostate adenocarcinoma." (PMID 27635108, 2016).
Burkitt lymphoma (1 paper, 2014). A rare form of malignant mature B-cell non-Hodgkin lymphoma. "This analysis revealed that PLAC1 is highly expressed in several Burkitt’s lymphoma cell lines as well as tumor cell lines derived from a number of other cancers." (PMID 24912876, 2014). "It is notable that of the B-cell lines tested, the highest expression of PLAC1 was observed in the type I BL lines (note: although P3HR1 is a Burkitt’s lymphoma derived cell line, these cells display a group II/III gene expression pattern)." (PMID 24912876, 2014). "The expression level of PLAC1 was significantly higher in four EBV positive Burkitt’s lymphoma cell lines compared with the EBV negative Burkitt’s lymphoma cell line, DG75." (PMID 24912876, 2014).
carcinosarcoma (1 paper, 2013). A malignant tumor composed of a mixture of carcinomatous and sarcomatous elements. "These were selected from the full panel of nine endometrioid adenocarcinomas, eight serous adenocarcinomas, and seven carcinosarcomas, all of which produced both PLAC1 and 18S rRNA amplicons." (PMID 23935632, 2013). "The importance of stage versus tumor type cannot be determined until PLAC1 expression is determined in higher stage endometrioid adenocarcinomas as well as lower stage serous adenocarcinomas and carcinosarcomas." (PMID 23935632, 2013). "Serous adenocarcinomas display a 6.6-fold higher PLAC1 expression (P < 0.01) relative to endometrioid adenocarcinomas, and carcinosarcomas display a 16.5-fold higher PLAC1 expression (P < 0.07) relative to endometrioid adenocarcinomas." (PMID 23935632, 2013).
cervical cancer (1 paper, 2023). A primary or metastatic malignant neoplasm involving the cervix. "Previous studies found that, abnormal expression of PLAC1 was found in nasopharyngeal carcinoma, cervical cancer and other malignant tumor tissues, and its expression level was closely related to poor prognosis of patients." (PMID 37568074, 2023).
choriocarcinoma (1 paper, 2025). An aggressive malignant tumor arising from trophoblastic cells. "PLAC1 has been shown to interact with DSG2 in a choriocarcinoma model." (PMID 40607388, 2025).
endometrial tumors (1 paper, 2013). "Endometrial tumors showed far less volatility in PLAC1 expression than did the cell lines." (PMID 23935632, 2013). "It is important to note that PLAC1 expression is seen in all twenty-four endometrial tumors irrespective of tumor type." (PMID 23935632, 2013).
gynecologic cancers (1 paper, 2014). "Taken together, our data and those produced by the studies cited above strongly suggest that PLAC1 should be considered a prime object of study in both gynecologic cancers and gestational disorders such as preeclampsia and preterm labor." (PMID 24757447, 2014). "More functional studies centered on the mature PLAC1 protein and its role in placental and fetal development and maintenance as well as in gynecologic cancer origin and growth must also be undertaken." (PMID 24757447, 2014).
Hydrocephalus (1 paper, 2013). Hydrocephalus is an active distension of the ventricular system of the brain resulting from inadequate passage of CSF from its point of production within the cerebral ventricles to its point of absorption into the systemic circulation. "Plac1 knockout mice have an increased risk to develop a lethal hydrocephalus indicating that Plac1 plays a major role in brain development." (PMID 24304549, 2013).
infiltrating ductal carcinomas (1 paper, 2013). "Indeed, it was shown that activation of PPARδ in the mouse mammary epithelium results in the appearance of estrogen receptor- and progesterone receptor-positive and ErbB2-negative infiltrating ductal carcinomas which are associated with an up-regulation of Plac1." (PMID 24304549, 2013).
leiomyosarcoma (1 paper, 2013). An uncommon, aggressive malignant smooth muscle neoplasm, usually occurring in post-menopausal women. "Of the two cell lines that failed to express PLAC1 mRNA one, RL95-2, is from a Grade 2 adenosquamous tumor, and the other, SK-UT-1b, is from a Grade 3 leiomyosarcoma." (PMID 23935632, 2013).
metastasis (1 paper, 2023). The spread or migration of cancer cells from one part of the body (where they first appeared) to another. "This study proves that PLAC1 and Netrin-1 are related to the degree of differentiation and lymph node metastasis of CRC liver metastasis, and can better judge the possibility of liver metastasis, which has certain clinical research value." (PMID 37568074, 2023).
ovarian tumors (1 paper, 2014). "In order to show that PLAC1 is potentially relevant to a number of research questions in OB/GYN, we report on PLAC1 expression in a selected panel that includes two choriocarcinoma cell lines, normal placental tissues, and endometrial and ovarian tumors." (PMID 24757447, 2014).
threatened abortion (1 paper, 2014). "While little is known regarding the function of PLAC1, lower circulating levels of PLAC1 mRNA in maternal serum have been shown to be associated with vaginal bleeding and threatened abortion prior to week 20 suggesting a key role for PLAC1 in trophoblast function." (PMID 24912876, 2014).
uterine carcinosarcoma (1 paper, 2022). A usually aggressive malignant neoplasm arising from the uterine corpus and less often the cervix. "Plac1 was highly expressed in tumor tissues compared to normal tissues in HNSC and uterine carcinosarcoma." (PMID 35814442, 2022).
uterine tumors (1 paper, 2013). "Whether this warrants a conclusion that tumors arising in uterine epithelium either preferentially or exclusively activate PLAC1 expression must await further study of a range of uterine tumors." (PMID 23935632, 2013).
cancer (29 papers, 2011 to 2025). A tumor composed of atypical neoplastic, often pleomorphic cells that invade other tissues. "Beyond its expression profile, PLAC1 has been implicated in promoting cancer cell proliferation, invasion, and migration." (PMID 40607388, 2025). "PLACenta-specific protein 1 (PLAC1) is a transmembrane antigen involved in trophoblast proliferation that is found to be associated with cancer progression." (PMID 36835024, 2023). "Plac1 was a risk factor in multiple cancers, and the risk score worked well in different TCGA cancer cohorts." (PMID 35814442, 2022). "We have recently produced a set of novel anti-human PLAC1 monoclonal antibodies (mAb) and have assessed their potential effectiveness in modulating different cancer-associated hallmarks including proliferation, invasion and resistance to apoptosis." (PMID 29042604, 2017). "Recently, we introduced PLAC1 (placenta-specific 1) as a novel member of cancer-associated placental genes." (PMID 24304549, 2013). "As a high expression of PLAC1 is well known to be associated with poor patient outcomes in a variety of cancers, the use of this compound in conjunction with conventional therapies may serve to improve these outcomes." (PMID 34577642, 2021). "PLAC1 is an important oncogenic factor and its expression is associated with invasiveness, metastasis, and proliferation of cancer cells 13,19 and is positively correlated with clinic-pathological parameters of some cancer types 18,24, 31,33." (PMID 32153735, 2020). "PLAC1 is among the genes overexpressed in human cancer and is selectively expressed in the placental syncytiotrophoblast in adult normal tissues, playing an essential role in normal placental and embryonic development." (PMID 36835024, 2023). "Plac1 expression has been observed in multiple cancer cells, including breast, lung, stomach, and colon cancers." (PMID 35814442, 2022). "In the two decades since PLAC1 was initially reported, many papers have demonstrated its co-opted expression in numerous human cancers." (PMID 34577642, 2021). "Other evidence that points to the similarity between cancer development and placenta formation is the expression of placenta-specific protein-1 (PLAC-1)." (PMID 33916290, 2021). "The preliminary aim of this study was to express the intact human PLAC1 protein on the surface of cancer cells as a model for future anti-PLAC1-based cancer immunotherapy." (PMID 32153735, 2020). "In contrast, there are plenty of reports indicating PLAC1 localization into cytoplasmic compartments of cancer tissues and cells 19,20,24,30,34." (PMID 32153735, 2020). "The aim of the current study was to express the intact human PLAC1 protein on plasma membrane of a eukaryotic cell as a model for future anti-PLAC1-based cancer immunotherapy." (PMID 32153735, 2020). "These include POLK, NIFK, SRGN, CAMP, CD109, and PLAC1 that are upregulated in several cancers resulting in metastasis and poor prognosis." (PMID 33110154, 2020). "Aberrant expression of PLAC1 is observed in various human cancers, where it is involved in the motility, migration, and invasion of tumor cells, which are associated with the phosphoinositide 3-kinase (PI3K)/AKT pathway." (PMID 32499871, 2020). "Various PLAC1 protein localizations have been reported in cancer cells and tissues including nucleus 22,24, cytoplasm 19,20,24,30,34, and plasma membrane 13,14, 34,35." (PMID 32153735, 2020). "We further show that PLAC1 signaling via FGFR2IIIb activates AKT phosphorylation in cancer cell lines." (PMID 32499871, 2020).
cancer (continued). "The aim of the present study was to express the intact human PLAC1 protein on plasma membrane of a eukaryotic cell as a model for future anti-PLAC1-based cancer immunotherapy." (PMID 32153735, 2020). "The role of PLAC1 and its cancer-selective, cell-surface expression make it an attractive candidate for antibody-mediated therapeutic strategies." (PMID 32499871, 2020). "Human PLAC1 protein at subcellular level was reported to be localized in cell nucleus, cytoplasm, and plasma membrane in normal and cancer tissues." (PMID 32153735, 2020). "Inhibition of PLAC1 in cancer cells leads to cell cycle arrest via a reduction in AKT phosphorylation and cyclin D levels." (PMID 32499871, 2020). "Placenta-specific protein 1 (Plac1) normally plays an important role in trophoblast invasion and migration but is also found to be expressed in a large range of human cancers." (PMID 33256070, 2020). "The roles of Plac1 in the progression of cancers have been directly ascribed to its processing activity that gives rise to the activation of cancer‐related signal pathway proteins‐Notch1 pathway." (PMID 29704427, 2018). "Placenta‐specific protein 1 (Plac1) is a cancer/testis antigen that plays a critical role in promoting cancer initiation and progression." (PMID 29704427, 2018). "In 50% of the cases where tissue blocks from the same serum donor were available to determine PLAC1 expression by IHC, 92% of DCIS, 97% of ER+/PR+/HER2- and 100% of HER2+ and TNBC cancers expressed PLAC1." (PMID 29432428, 2018). "In a similar context, PLAC1 expression detected by IHC was upregulated in other cancers, such as serous endometrial adenocarcinoma and late stage colon and liver cancer." (PMID 29432428, 2018). "Many genes normally expressed in the embryo become reactivated in cancer cells, and PLAC1 was the first such cancer/testis gene that related placentation to cancer." (PMID 29432428, 2018). "While its expression is mostly restricted to placenta and testis in normal tissues, Plac1 is frequently activated and highly expressed in wide variety of human cancers." (PMID 29704427, 2018). "Our data showed that the extent of apoptosis by anti-PLAC1-ADC corresponded to the percent of PLAC1 positive cells pointing to the selective action of anti-PLAC1-ADC on cancer cells." (PMID 29042604, 2017). "MIR503HG and LINC00629 genes are located in the same region as PLAC1, whose expression is restricted to placenta and recently was found to be expressed in cancer cells." (PMID 27023770, 2016). "We have shown here that PLAC1 expression appears to be ubiquitous in cancers originating in uterine epithelium." (PMID 23935632, 2013). "Several studies have shown that the PLAC1 gene is turned on in a variety of human solid tumors and cancer cell lines." (PMID 23935632, 2013). "It seems reasonable to assume that it is these very properties, derived from the gene's normal function, which lead cancer cells to coopt the PLAC1 gene." (PMID 23935632, 2013). "The complex expression pattern of PLAC1 in placenta and cancer is regulated by two distinct promoters." (PMID 24304549, 2013). "P2-driven transcription accounts for the majority of PLAC1 message in human placenta, but P1-driven transcription accounts for the majority of PLAC1 message in several cancer cell lines." (PMID 23935632, 2013). "Tumor-promoting functions of PLAC1 can be antagonized by specific antibodies, thereby qualifying PLAC1 as promising candidate for targeted therapies of cancer." (PMID 24304549, 2013). "Exploring the targeting of PLAC1 to enhance NK cell-mediated anti-tumor responses could lead to the development of new immunotherapies that increase NK cell cytotoxicity or harness PLAC1’s immunogenic potential to improve cancer treatment outcomes." (PMID 40607388, 2025). "Notably, Plac1+ tumor cells not only enhance tumor malignant characteristics and tumor growth in a cancer‐autonomous way, but also shape an immunosuppressive TME characterized by Treg infiltration." (PMID 40056047, 2025).